AMBRA1 (autophagy and beclin 1 regulator 1)
Diseases named in the same sentence as AMBRA1 in open-access papers (continued):
Sharing a sentence is not in itself a finding about the gene and the disease.
astrocytoma (1 paper, 2021).
benign prostatic hyperplasia (1 paper, 2022). A non-cancerous nodular enlargement of the prostate gland. "It has been shown that the increased expression of AMBRA1 in PCa has a significant correlation with Gleason score, and the expression of AMBRA1 and SQSTM1 mRNA is significantly upregulated in PCa samples compared to benign prostatic hyperplasia, which may potentially contribute to PCa progression." (PMID 36361635, 2022).
chronic kidney disease (1 paper, 2024). Impairment of the renal function secondary to chronic kidney damage persisting for three or more months. "TRIM72 and autophagy and beclin 1 regulator 1 (AMBRA1) levels have been shown to be significantly low in patients with chronic kidney disease (CKD)." (PMID 38225560, 2024).
diabetic retinopathy (1 paper, 2025). "Modulating Ambra1 activity could potentially serve as a new therapeutic approach for managing inflammation in diabetic retinopathy." (PMID 41001311, 2025).
endometriosis (1 paper, 2024). The growth of functional endometrial tissue in anatomic sites outside the uterine body. "Mechanistically, the mTOR inhibition acts as a hub to activate autophagy mechanisms through increased expression of Beclin1, LC3II, Bnip3, Ambra1, and Parkin in a rat model of endometriosis." (PMID 38645639, 2024). "In a rat model of endometriosis, the expression of mTOR was increased, and the expression of Beclin1, Bnip3, Ambra1, LC3II, and Parkin was decreased, suggesting that the autophagy level is decreased in ectopic endometrium compared to eutopic endometrium and normal endometrium." (PMID 38645639, 2024).
female infertility (1 paper, 2023). Diminished or absent ability of a female to achieve conception. "Future insights into Ambra1 role in gonadal development and physiology may help uncover new aspects of male and female infertility, a pathological problem in which many cases are still considered idiopathic." (PMID 37106439, 2023).
fibrosarcoma (1 paper, 2014). A malignant mesenchymal fibroblastic neoplasm affecting the soft tissue and bone. "In a previous study, calpains and caspases were shown to be responsible for Ambra1 cleavage in fibrosarcoma cell lines." (PMID 24587252, 2014).
gastric adenocarcinoma (1 paper, 2024). "Loss of AMBRA1 aids in inhibiting cell invasion and metastasis of gastric adenocarcinoma." (PMID 39720719, 2024).
gastric cancer (1 paper, 2024). A primary or metastatic malignant neoplasm involving the stomach. "This research aims to elucidate the molecular mechanisms underlying AMBRA1’s involvement in gastric cancer progression." (PMID 39720719, 2024). "Furthermore, the increased drug sensitivity observed in AMBRA1 deficient cells suggests potential therapeutic benefits of AMBRA1 suppression in the treatment of gastric cancer." (PMID 39720719, 2024). "In addition, AMBRA1 deficiency promoted DNA damage, increased oxidative stress, and shortened telomere length, resulting in gastric cancer cell senescence, apoptosis, and ultimately, cell death." (PMID 39720719, 2024). "In gastric cancer, we found that AMBRA1-KO dramatically reduced the levels of vimentin and N-cadherin and increased the expression of E-cadherin." (PMID 39720719, 2024). "An AGS gastric cancer xenograft model was constructed to further verify the role of AMBRA1 in the development of STAD." (PMID 39720719, 2024). "AMBRA1 depletion in AGS gastric cancer cells led to significant changes in cell morphology and behavior." (PMID 39720719, 2024). "Given these insights, our study aims to elucidate the role of AMBRA1 in regulating tumor plasticity in gastric cancer." (PMID 39720719, 2024). "Taken together, these results provide compelling in vivo evidence for the critical role of AMBRA1 in maintaining tumor growth and cellular integrity in gastric cancer." (PMID 39720719, 2024). "Further investigation revealed that the deletion of AMBRA1 prevented the growth of gastric cancer cells and encouraged a reduction in cyclinD1 levels in human gastric cancer AGS cells." (PMID 39720719, 2024). "A mixture of 5×106 KO AMBRA1 AGS gastric cancer cells resuspended in sterile PBS and Ceturegel matrix gel into the flank of 6-7 week-old male BALB/c-nude mice, with groups of six mice per experiment." (PMID 39720719, 2024). "Furthermore, there was a noticeable decrease in the migration and invasion of gastric cancer cells in AMBRA1-KO." (PMID 39720719, 2024). "Based on the correlation of AMBRA1 expression with patient survival, we hypothesized that AMBRA1 plays a critical role in promoting gastric cancer cell growth and invasion." (PMID 39720719, 2024). "Western blot, Flow Cytometry (FCM) assay, trans-well assay, wound healing assay, MTT, Reactive Oxygen Species (ROS) assay, Reverse Transcription Quantitative Polymerase Chain Reaction (RT-qPCR) and staining were performed to study the effects of AMBRA1 in AGS human gastric cancer cells." (PMID 39720719, 2024). "The relationship between AMBRA1 expression and immune cell infiltration, particularly T cells, underscores the importance of understanding how AMBRA1 may influence the immune microenvironment in gastric cancer." (PMID 39720719, 2024). "Additionally, we generated AMBRA1 knockdown (KD), KO and overexpression models in the AGS gastric cancer cell line." (PMID 39720719, 2024). "In the context of gastric cancer, extensive research on the role of AMBRA1 is still lacking." (PMID 39720719, 2024).
germ cell tumor (1 paper, 2023). A benign or malignant, gonadal or extragonadal neoplasm that originates from germ cells. "Finally, in agreement with the AMBRA1 role as a tumor suppressor, among the mutant males we analysed we found two cystic degenerations of the seminiferous tubules, a pre-cancer condition, two seminomas and an undifferentiated germ cell tumor." (PMID 37106439, 2023).
hamartoma (1 paper, 2022). A benign and excessive tumor-like growth of mature cells and normal tissues which grow in a disorganized pattern. "Considering uncontrolled cell proliferation as a hamartoma characteristic and AMBRA1 as a newly recognized tumor suppressor, we speculated that AMBRA1 depletion might affect the cell proliferation rate." (PMID 36232425, 2022).
Headache (1 paper, 2023). Cephalgia, or pain sensed in various parts of the head, not confined to the area of distribution of any nerve. "Additionally, among the overlapping genes between migraine and headache with glycemic traits, five genes have previously been associated with migraine (THADA, EHMT2, AMBRA1, and SMG6) and headache (ATG13); now, these genes are also implicated in glycemic traits." (PMID 36808568, 2023). "Furthermore, five of the 30 genome-wide significant genes overlapping migraine and more than one glycemic trait were the nearest genes to a lead migraine SNP (THADA, EHMT2, AMBRA1, and SMG6) and headache SNP (ATG13)." (PMID 36808568, 2023).
Hyperglycemia (1 paper, 2018). An increased concentration of glucose in the blood. "Here, we show the existence of a prediabetic state in Ambra1 mice, characterized by hyperglycemia, intolerance to glucose and insulin resistance." (PMID 30532260, 2018).
hypovitaminosis (1 paper, 2025). "The expression of AMBRA1 followed a similar pattern, with higher levels observed in treated persons with normal vitamin D3 levels compared to those with hypovitaminosis." (PMID 40514685, 2025). "Regarding AMBRA1 expression, densitometric analysis showed a higher level in treatment-naїve patients with a normal concentration of vitamin D3 compared to patients who showed hypovitaminosis (p < 0.05)." (PMID 40514685, 2025).
hypoxic-ischemic encephalopathy (1 paper, 2025). "In hypoxic-ischemic encephalopathy (HIE), treatment with CpG-ODN increases the phosphorylation of AMPK and its downstream targets (including ULK1, AMBRA1, LC3II/I, and LAMP1) and inhibition of TLR9 or AMPK reverses these effects, leading to decreased autophagy and poorer neurobehavioral outcomes." (PMID 40558558, 2025).
injury (1 paper, 2018). Damage inflicted on the body as the direct or indirect result of an external force, with or without disruption of structural continuity. "Oxidation of dietary fat, already reduced in Ambra1 mice before the CCI, was further reduced after nerve injury." (PMID 30532260, 2018).
Listeria infection (1 paper, 2019). "We were struck by the modification of four key regulators of autophagy by ISGylation, in particular the modification of mTOR and WIPI2 following infection in wild-type animals following Listeria infection and modification of AMBRA1 and RAB7 following infection in USP18C61A/C61A animals." (PMID 31772204, 2019).
lymph node metastasis (1 paper, 2019). "However, high levels of AMBRA-1 protein have been found in GC patients and they appeared significantly related to depth of invasion and lymph node metastasis." (PMID 30893939, 2019).
macular degeneration (1 paper, 2023). Loss of vision in the central portion of the retina (macula), secondary to retinal degeneration. "This suggests that the AMBRA1-dependent autophagy initiation complex may be induced to counteract the stress that causes RPE dysfunction and cell loss, a key feature of macular degeneration." (PMID 35875981, 2023).
migraine (1 paper, 2023). "Additionally, we note that many significant genes (e.g., AMBRA1, ATG13, ARHGAP1, CKAP5, LRP4, and DDB2) have been associated with migraine, headache, and proinsulin." (PMID 36808568, 2023).
myocardial ischemia (1 paper, 2020). A disorder of cardiac function caused by insufficient blood flow to the muscle tissue of the heart. "Therefore, we investigated the role that Ambra1 plays in myocardial ischemia and reperfusion and its mechanisms." (PMID 33083461, 2020). "Ambra1 has been reported to regulate ROS, and ROS is an important cause of MIRI; thus, regulating ROS may also change the outcomes of myocardial ischemia and reperfusion." (PMID 33083461, 2020).
neuroblastoma (1 paper, 2018). Neuroblastoma (NB) is the most common solid, extracranial childhood tumor. "In this study, we investigated the potential neuroprotective effect of AMBRA1-induced mitophagy against 6-hydroxydopamine (6-OHDA)- and rotenone-induced cell death in human neuroblastoma SH-SY5Y cells." (PMID 29755319, 2018). "Since NIX, similar to AMBRA1, induces alternative mitophagy (PINK1- and PARKIN-free), it would be of the highest interest to test in this context whether NIX-mediated mitophagy can rescue cell death following 6-OHDA or rotenone treatments in human neuroblastoma cell lines." (PMID 29755319, 2018).
osteosarcoma (1 paper, 2021). A usually aggressive malignant bone-forming mesenchymal neoplasm, predominantly affecting adolescents and young adults. "AMBRA1 is significantly associated to the survival of osteosarcoma and plays a protective role." (PMID 34513835, 2021). "In this study, AMBRA1 was closely related to the prognosis of osteosarcoma." (PMID 34513835, 2021). "Therefore, how AMBRA1 may be involved in the pathology of osteosarcoma requires additional investigation." (PMID 34513835, 2021). "Our results showed that compared with osteoblasts, AMBRA1 was down-regulated in U2OS and 143B, and while MYC and VEGFA were up-regulated in osteosarcoma cells." (PMID 34513835, 2021).
ovarian carcinoma (1 paper, 2025). A malignant neoplasm originating from the surface ovarian epithelium. "AMBRA1 is reported to be an important regulator of autophagy and apoptosis in ovarian cancer cells under the influence of cisplatin, which can maintain the balance between autophagy and apoptosis." (PMID 38393538, 2025).
prediabetes (1 paper, 2018). "We demonstrated that these conditions of borderline diabetes and defective autophagy are the mechanisms responsible for the exacerbation of allodynia previously showed in Ambra1 mice." (PMID 30532260, 2018).
sarcopenia (1 paper, 2022). Progressive decline in muscle mass due to aging which results in decreased functional capacity of muscles. "In general, decreased levels of mitophagy markers such as PINK1, parkin BNIP3, NIX, PHB2, FUNDC1, and AMBRA1 are associated with a reduced quality of life in sarcopenia associated with aging." (PMID 36561214, 2022). "In addition, reduced levels of mitophagy markers such as PINK1, Parkin, BNIP3, NIX, PHB2, FUNDC1, and AMBRA1 negatively impact sarcopenia-related muscle weakness and the quality of life in the elderly." (PMID 36561214, 2022).
Sepsis (1 paper, 2025). Sepsis is defined as life-threatening organ dysfunction caused by a dysregulated host response to infection. "MAVS regulates cellular apoptosis through interaction with AMBRA1, activates the NF-κB pathway during viral infections to trigger inflammatory factor release, and inhibiting MAVS can significantly reduce inflammatory responses and improve sepsis outcomes." (PMID 40766842, 2025).
situs inversus (1 paper, 2022). A congenital condition in which there is complete right-to-left reversal of the position of the major thoracic and abdominal organs (that is, they are arranged in a mirror image of the normal positioning). "Our observation of situs inversus added further emphasis to the significant role of AMBRA1 in primary cilia regulation and congenital defects." (PMID 36232425, 2022).
thymic lymphoma (1 paper, 2025). "In the case of thymic lymphoma, which was frequently observed in Ambra1 cKO mice, the enlarged thymus compressed the lungs and caused lethal respiratory distress (arrowhead)." (PMID 40734673, 2025).
tonic-clonic seizures (1 paper, 2017). "This early resistance turned into the opposite response at older age: Number of tonic-clonic seizures and duration of whole-body seizures were enhanced in 3-months (data not shown) and 13-months-old Ambra1+/− females versus WT, also resulting in reduced survival." (PMID 28994820, 2017).
tubular carcinomas (1 paper, 2019). "Interestingly, in the low-grade tubular carcinomas only two cases exhibited an immunopositive cytoplasmic reaction for LC3A/B and Beclin 1, whereas four different low-grade cases showed AMBRA-1 positive expression." (PMID 30893939, 2019).
type 1 diabetes (1 paper, 2025). "Subsequently, we performed immunofluorescence staining for cyclin D3 (a cell cycle-related protein) and GS (a Müllerian glial marker) using eyes from control mice, Ambra1-deficient mice, and STZ-induced type 1 diabetes model mice." (PMID 41001311, 2025). "Immunohistochemical analysis was conducted on retinal sections from four experimental groups: Ambra1 knockout mice, control mice, and their respective counterparts with streptozotocin-induced type 1 diabetes." (PMID 41001311, 2025). "This study employed Ambra1 cKO mice to investigate retinal cell proliferation and inflammatory responses in an STZ-induced type 1 diabetes model." (PMID 41001311, 2025).
ulcerative colitis (1 paper, 2025). An inflammatory bowel disease involving the mucosal surface of the large intestine and rectum. "Elevated AMBRA1 expression in inflamed colon tissues from ulcerative colitis patients is negatively correlated with decreased NRF2 protein levels." (PMID 39887666, 2025).
tumor (47 papers, 2014 to 2026). "AMBRA1 has been proposed to be a tumor suppressor, and loss of AMBRA1 promotes cancer cell growth and invasion." (PMID 40110710, 2025). "Reported evidence indicate that AMBRA1 deficient mice models represent accelerated tumor growth, invasiveness, and metastasis in BRAF/PTEN melanoma phenotype via increased activity of Focal Adhesion Kinase 1 (FAK1)." (PMID 40248706, 2025). "AMBRA1 was recently described as a potent tumor suppressor, which regulates the stability of D-type cyclins and S phase entry, and loss of AMBRA1 has been suggested to decrease sensitivity to CDK4/6 blockade." (PMID 39617889, 2024). "In vivo studies confirmed the tumor-suppressive effects of AMBRA1 loss, resulting in reduced tumor growth and increased cellular senescence." (PMID 39720719, 2024). "AMBRA1, a key adaptor protein of the autophagy signaling network, is a tumor suppressor and mutated in a wide range of tumors." (PMID 36232425, 2022). "AMBRA1-deficient tumor cells were more likely to grow when injected into nude mice than wild-type tumor cells, implying a negative relationship between AMBRA1 and tumorigenesis." (PMID 34769507, 2021). "AMBRA1 is associated with a variety of pathological processes in cancer cells, but may have different functions in different tumour microenvironments or genetic backgrounds." (PMID 40464146, 2025). "In contrast to the expected increase in S phase cells upon cyclin D stabilization as a result of AMBRA1 deficiency, we find that tumor suppressive activity of AMBRA1 in a subset of ATRT cells is directly correlated with deregulation of mitotic factors and a concomitant increase in G2/M phase cells." (PMID 39617889, 2024). "In mice, Ambra1 is associated with tumor formation and acts as a tumor suppressor." (PMID 38067169, 2023). "Interestingly, although differently, mutations of the conserved L110 (L→F) and P170 (P→S) residues were found implicated in functions of AMBRA1 recently reported to be relevant in terms of tumor growth and progression." (PMID 36243772, 2022). "AMBRA1 loss is therefore associated with a proliferative phenotype: AMBRA1‐mutant mice show embryonic lethality due to hyperproliferation of neuronal precursors, whereas AMBRA1 haploinsufficiency is associated with increased cellular proliferation and spontaneous tumour formation in an animal model." (PMID 34773645, 2022). "Targeting TGF‐β2 signalling may therefore represent a novel adjuvant treatment strategy for high‐risk early‐stage tumours with loss of epidermal AMBRA1." (PMID 34773645, 2022). "Based on this evidence, we can thus speculate that displacement of patterning regulators, unbalanced cell proliferation, and tumor susceptibility (all been observed in AMBRA1-deficient models), are due, at least in part, to the role of AMBRA1 in mitotic spindle orientation." (PMID 37584777, 2023). "The loss of the AMBRA1 protein drives the tumor formation in mice and is linked with worse outcomes in some human tumors, and they also found that a lack of AMBRA1 may make some tumors resistant to drugs called CDK4/6 inhibitors, which are a promising new class of cancer treatments." (PMID 34901460, 2022). "Collectively, these results strongly suggested that AMBRA1 serves as a tumor suppressor in vivo condition." (PMID 40734673, 2025). "While the inhibitory effect of AMBRA1‐oe on tumour growth was weakened by miR‐1178 overexpression (p < 0.05 and p < 0.01)." (PMID 40464146, 2025). "In comparison to control mice, the AMBRA1 overexpression group inoculated in nude mice had reduced tumour volume and weight (p < 0.05 and p < 0.01)." (PMID 40464146, 2025).